RIF1 (replication timing regulatory factor 1)
Diseases named in the same sentence as RIF1 in open-access papers (continued):
Sharing a sentence is not in itself a finding about the gene and the disease.
lung adenocarcinoma (3 papers, 2018 to 2025). A carcinoma that arises from the lung and is characterized by the presence of malignant glandular epithelial cells. "We observed an increased total RIF1 mRNA in colon (COAD), lung adenocarcinoma (LUAD), and lung squamous (LUSC) cancers and decreased expression in thyroid cancer (THCA) compared to matched normal tissues." (PMID 40806439, 2025). "Total RIF1 mRNA expression was significantly downregulated in breast invasive carcinoma (BRCA) relative to the matched normal breast tissue, while RIF1 expression levels were relatively upregulated in colon adenocarcinoma (COAD), lung adenocarcinoma (LUAD), and lung squamous carcinoma (LUSC)." (PMID 41489901, 2025).
breast adenocarcinoma (2 papers, 2018 to 2021).
fibrosarcoma (2 papers, 2016 to 2019). A malignant mesenchymal fibroblastic neoplasm affecting the soft tissue and bone. "As part of our ongoing studies of heat shock response, we conducted microarray studies of radiation induced mouse fibrosarcoma cell line, RIF-1, and its thermotolerant variant, TR-RIF-1 (TR)." (PMID 30796345, 2019).
gastric cancer (2 papers, 2015 to 2021). A primary or metastatic malignant neoplasm involving the stomach.
Obesity (2 papers, 2022 to 2025). Accumulation of substantial excess body fat. "Therefore, RIF1, as an obesity-associated maternal factor, may be involved in epigenetic remodeling." (PMID 35123389, 2022). "Taken together, these results showed that obesity induced an elevated RIF1, the abnormal totipotency of zygotes, and the asymmetric epigenetic remodeling of both DNA methylation and histone modifications." (PMID 35123389, 2022). "Accordingly, we propose that RIF1 may be a maternal epigenetic regulator during ZGA in a model of obesity." (PMID 35123389, 2022). "However, it has not been reported whether the RIF1 levels of oocytes are changed and further cause epigenetic abnormalities during ZGA in a model of obesity." (PMID 35123389, 2022).
sarcoma (2 papers, 1981 to 1991). A usually aggressive malignant neoplasm of the soft tissue or bone. "The effect has been studied of adding either misonidazole (MISO) or the radioprotective drug, WR 2721, to cyclophosphamide (CY) treatment of mice bearing either the RIF-1 or KHT sarcomas." (PMID 6264941, 1981). "Large increases in the Pi/total phosphate ratio were found with the murine sarcomas, KHT and RIF-1 implanted into C3H/He mice." (PMID 1931606, 1991).
teratocarcinoma (2 papers, 2015 to 2016). A germ cell tumor characterized by the presence of an embryonal carcinoma component and a teratoma component. "On the basis of these results, it is worthwhile investigating whether control of Rif1 levels by drugs could benefit the treatment of teratocarcinoma." (PMID 25569105, 2015). "Comparison of the expression of Smad3 and Rif1 between teratoma cells and teratocarcinoma cell lines F9 and P19 revealed that Smad3 was significantly lower in teratocarcinoma cells than teratoma cells, whereas Rif1 is significantly higher in teratocarcinoma cells than teratoma cells." (PMID 25569105, 2015).
teratoma (2 papers, 2015 to 2023). A non-seminomatous germ cell tumor characterized by the presence of various tissues which correspond to the different germinal layers (endoderm, mesoderm, and ectoderm). "To further examine the correlation between Smad3 and Rif1, we examined the expression profiles of these two genes in mouse ESCs, mouse embryonic fibroblasts (MEFs), teratoma cells and mouse ESC-differentiated cells." (PMID 25569105, 2015). "However, Rif1-KO promoted the development of three germ layers formation in teratomas." (PMID 36971904, 2023).
autoimmune polyendocrinopathy (1 paper, 2024). A group of diverse conditions that are characterized by spontaneous, multi-organ autoimmunity, which target both endocrine (adrenal, gonad, pancreatic islet cells, parathyroid, pituitary, thyroid) and non-endocrine (gastrointestinal, integumentary, lymphatic) tissues. "In the RIF-1 IVIg group, one patient with autoimmune polyendocrinopathy was diagnosed with pre-eclampsia at 37 weeks and was induced to deliver a healthy 3265 g daughter." (PMID 38365988, 2024).
bipolar disorder (1 paper, 2024). A disorder of the brain that causes unusual shifts in mood, energy, activity levels and the ability to carry out day-to-day tasks. "VWA8 (von Willebrand domain-containing protein 8), SNAP29 (Synaptosomal-associated protein 29), RIF1 (Replication Timing Regulatory Factor 1), AQP4 (Aquaporin-4) and GSTM3 (Glutathione S-Transferase Mu 3) were some relevant differentially expressed genes detected in the bipolar disorder datasets." (PMID 39727940, 2024).
chronic myelogenous leukaemia (1 paper, 2016). "To test the applicability of the All-in-One Cas9D10A nickase vector system and screening approaches in other cell lines, we targeted the DDR genes MDC1, 53BP1 and RIF1 in human aneuploid osteosarcoma (U2OS) cells and haploid chronic myelogenous leukaemia derived (HAP1) cells." (PMID 27079678, 2016).
gastric adenocarcinoma (1 paper, 2023). "One of these patients had gastric adenocarcinoma, and was found to have somatic alterations in RIF1 and HELQ, both of which are genes known to be involved in the HR pathway." (PMID 36964191, 2023).
glioma (1 paper, 2021). A benign or malignant brain and spinal cord tumor that arises from glial cells (astrocytes, oligodendrocytes, ependymal cells). "GP130, low-density lipoprotein receptor-related protein 12 (LRP12), and Rap1 interacting factor 1 (RIF1), as candidate palmitoylated proteins for experimental validation, may be associated with glioma development and malignant progression." (PMID 33541421, 2021).
kidney cancer (1 paper, 2025). Primary or metastatic malignant neoplasm involving the kidney. "We found that high RIF1 expression is associated with improved patient survival in kidney cancer." (PMID 40806439, 2025).
liver cancer (1 paper, 2017). An epithelial or non-epithelial malignant neoplasm that arises from the liver. "and cancer driver genes (ATRX, MDC1, RIF1, APC and PCM1) showed a phosphorylation related signal transition network affecting cell proliferation ability and revealed the extreme complex nature of phosphoproteome transformation in liver cancer cells." (PMID 28883432, 2017).
ovarian tumour (1 paper, 2024). "As it turns out, Rif1 binds directly to the promoter for hTERT allowing its expression, while Rif1 knockout inhibited ovarian tumour growth." (PMID 37548940, 2024).
skin cancer (1 paper, 2022). "In skin cancer, PAXIP1, EXO1, and RIF1 associated with dHRVAE1, the component correlating with SNV signature 3 mutations." (PMID 35764656, 2022).
squamous cell carcinoma (1 paper, 2017). A carcinoma arising from squamous epithelial cells. "We found that RIF1 had the positive strong expression in squamous cell carcinoma, and negative weak expression in normal cervix squamous epithelial cells." (PMID 29291010, 2017).
thyroid tumours (1 paper, 2025). "We find that overall RIF1 mRNA expression levels are increased in colon and lung tumours and decreased in thyroid tumours when compared to matched normal tissue controls from the same patients." (PMID 40806439, 2025).
tumor (32 papers, 1983 to 2026). "Future work will determine roles and consequences of RIF1 splice variant expression changes in these tumour types." (PMID 40806439, 2025). "To investigate the role of RIF1 splice variants in cancer, we used transcript analysis data held by TCGA SpliceSeq to analyse inclusion of Exon 31 in RIF1 transcripts from different tumour types." (PMID 40806439, 2025). "We performed paired Wilcoxon signed-rank tests to compare RIF1 mRNA expression between normal and tumour samples." (PMID 40806439, 2025). "Here, we investigate differential expression and splicing of RIF1 in cancer cell lines following replication stress and in patients using matched normal and tumour data from The Cancer Genome Atlas (TCGA)." (PMID 40806439, 2025). "The earlier analysis performed a chemosensitivity study, where tumour samples were collected from 89 patients before chemotherapy, then RIF1 expression was quantified and correlated with their response to the drug." (PMID 40806439, 2025). "Research into the function of Rif1 in tumourigenesis has yielded new solutions and alternative treatment pathways for various tumour types." (PMID 37548940, 2024). "As in previous studies, inhibition of Rif1 expression limited tumour growth, while its overexpression promoted tumour growth through activation of the PP1-AXIN trail resulting in induction of Wnt/β-catenin pathways." (PMID 37548940, 2024). "Nonetheless, we found 46 genes that carried either genomic or transcriptional alterations in all three resistant tumor groups, including 8 genes (Parp3, Gstm1, Il18, Padi4, Dnmt3b, Psrc1, Rif1, and Ankrd26) involved in DDR." (PMID 37209095, 2023). "Together, these results indicate that RIF1 promotes tumor growth and stem cell-like phenotype in EOC via hTERT signaling pathway." (PMID 30075819, 2018). "All these results indicate that RIF1 regulates EOC tumor growth and progression through binding to the promoter of hTERT and regulating hTERT expression." (PMID 30075819, 2018). "In summary, our study has demonstrated that as an oncogene, RIF1 facilitates tumor cell growth and CSC-like traits in EOC." (PMID 30075819, 2018). "In human tumors, expression of the repair proteins RAD51, KU70 and RIF1 was strongly suppressed in hypoxic peri-necrotic tumor areas." (PMID 29156796, 2017). "Genotyping of tumor samples confirmed the integration of Rif1 shRNA in the teratoma cells produced by Rif1 shRNA-transduced Smad3−/− ESCs." (PMID 25569105, 2015). "When RIF-1 EGFP tumours were treated under the same conditions with BPD-PDT we observed interesting and surprising differences in the responses." (PMID 16421588, 2006). "Firstly the tumour shrinkage was more marked with RIF-1 EGFP tumours than was found with RIF-1 tumours." (PMID 16421588, 2006). "Blood (100 μl) was withdrawn via the orbital plexus from mice bearing RIF-1 or RIF-1 EGFP tumours, allowed to clot and serum obtained." (PMID 16421588, 2006). "Five mice that had been cured of RIF-1 EGFP tumours and rejected a subsequent rechallenge with RIF-1 EGFP tumour cells were rechallenged with one million wild-type RIF-1 cells together with naïve mice." (PMID 16421588, 2006). "There were complete cures and 100% mouse survival of RIF-1 EGFP while RIF-1 wild-type tumours all recurred." (PMID 16421588, 2006). "Five murine tumours (MAC16, MAC26, NT, SCCVII and RIF-1) have been used to investigate the anti-tumour effects of AQ4N." (PMID 10864207, 2000). "The ability of the calcium antagonists, cinnarizine and flunarizine, to enhance the radiosensitisation produced by the administration of an erythrocyte transfusion to anaemic, RIF-1 or SCCVII/St tumour bearing mice was determined." (PMID 2803913, 1989). "The elevated expression of RIF1 within certain tumours may affect their vulnerability to specific DNA-damaging treatments, offering a potential avenue for targeted therapeutic strategies." (PMID 40806439, 2025).
tumor (continued). "Based on the clinical importance of chemotherapeutic agents that interfere with the DNA replication process, investigating RIF1 isoform expression may also provide insights into how tumour cells respond to replication-inhibiting therapeutic drugs." (PMID 40806439, 2025). "A direct mechanism in which Rif1 promotes tumour growth has also been revealed." (PMID 37548940, 2024). "If this dose-limited radioresistance could be maximized in normal cells or minimized in tumor cells by the regulation of RIF1, radiation therapy might be more effective for controlling tumors in some tissues." (PMID 32434870, 2020). "Consistently, overexpression of hTERT could rescue the inhibition effect of RIF1 knockdown on tumor growth and sphere formation." (PMID 30075819, 2018). "Tumor weight in RIF1 knockdown group were greatly reduced compared to the control group." (PMID 30075819, 2018). "Tumor cells with RIF1 knockdown grew more slowly than the vector control in the same mouse." (PMID 30075819, 2018). "Our study has provided new insights for the understanding of the regulation of hTERT in EOC tumorigenesis, revealing that RIF1 is a pivotal regulatory molecule in the hTERT signaling pathway for tumor progression as well as a potentially effective target for EOC therapy." (PMID 30075819, 2018). "Tumor tissues derived from RIF1 knockdown H1299 cells exhibited decreased positivity for the proliferation index Ki-67 compared with the control groups, indicating that RIF1 promotes NSCLC cell growth in vivo." (PMID 30237512, 2018). "Since hTERT signaling is considered crucial for carcinogenesis and the maintenance of cancer cellular stemness of EOC, then we explored whether RIF1 could enhance tumor growth and CSC-like traits in EOC via hTERT signaling." (PMID 30075819, 2018). "However, the finding that wild-type RIF-1 tumours grew significantly slower in mice cured from RIF-1 EGFP tumours than in naïve mice was surprising." (PMID 16421588, 2006). "The RIF-1 tumours grew in all the mice but again the rate of growth of RIF-1 cells in mice cured of RIF-1 EGFP tumours by PDT was significantly slower than the rate in naïve mice (P<0.001 by comparing slopes of logarithmic transformed data) than in naïve mice." (PMID 16421588, 2006). "We will investigate whether mice cured of RIF-1 EGFP tumours also have immunity against other EGFP-expressing tumours cells syngeneic to C3H mice." (PMID 16421588, 2006). "However, the growth rate of the surgically cured mice rechallenged with RIF-1 EGFP was significantly slower than the growth rate of naive RIF-1 EGFP tumours (P<0.001 by comparing slopes of logarithmic transformed data)." (PMID 16421588, 2006). "However, major intertumoral differences between the permeability of vessels present in RIF-1 and R1 tumours were found." (PMID 15812555, 2005). "Consistent with this hypothesis, our fluorescence microscopy analysis of RIF-1 tumour sections revealed a more homogeneous vessel distribution in small tumours, with a high percentage of functional vessels and a lack of necrotic areas." (PMID 15812555, 2005). "Since Evans blue accumulated more in RIF-1 than in R1 tumours over a large tumour weight range, it could be concluded that the larger amount of marker extravasated in RIF-1 tumours was due to an increased permeability of the tumour vessels." (PMID 15812555, 2005). "However, the observation that RIF-1 EGFP tumours have the same growth rate in C3H mice as wild-type RIF-1 tumours suggests that another immunopotentiating stimulus is necessary to engender the full immune response against the tumour." (PMID 16421588, 2006). "We demonstrated the expression patterns of ARID1a/BAF250a and RIF1 in EOC, establishing their potential relevance in the context of tumor biology and malignant transformation." (PMID 42274628, 2026).
tumor (continued). "However, CRISPR-Cas9-mediated inactivation of RIF1 did not reduce PARPi sensitivity in cultured KB2P tumor cells, suggesting that RIF1 loss might only drive resistance in vivo or that it is a consequence of PARPi treatment rather than causal to resistance." (PMID 37209095, 2023). "Additionally, Rif1 may directly foster tumor cell proliferation." (PMID 34781085, 2021). "Then we examined the impact of hTERT overexpression on tumor growth and the CSC-like traits of RIF1-suppressed EOC cells." (PMID 30075819, 2018). "Then we examined the impact of silencing hTERT on tumor growth and the CSC-like traits of RIF1-overexpressed EOC cells." (PMID 30075819, 2018). "We injected RIF-1 or RIF-1 EGFP (stably transduced with a retroviral vector) cells in the leg of C3H/HeN mice and both the cells and tumour grew equally well." (PMID 16421588, 2006). "Mice that were cured of RIF-1 EGFP tumours by BPD-PDT, mice that had their RIF-1 EGFP tumours surgically removed and untreated control mice were rechallenged by a second injection of 1 million RIF-1 EGFP cells after they had been tumour-free for 60 days." (PMID 16421588, 2006). "We examined the relationship between the cytotoxicity of tirapazamine under hypoxic conditions and tirapazamine-induced DNA strand breaks in murine (SCCVII, EMT6, RIF-1) and human (HT1080, A549, HT29) tumour cell lines." (PMID 8611431, 1996). "In a preliminary study large single doses of benznidazole (BENZ), misonidazole (MISO), desmethylmisonidazole (DMM), and SR-2508 were found to give similar enhancement of the RIF-1 and SCC VII/St tumours." (PMID 6229264, 1984). "The concentration of CCNU was measured in 4 tumours: the KHT, RIF-1 and EMT6 mouse tumours, and the HT29 xenograft." (PMID 6849803, 1983). "Tumor tissues derived from RIF1 knockdown cells exhibited reduced positivity for Ki67 and hTERT compared with the control groups, indicating that RIF1 promoted hTERT expression and EOC tumor growth in the mouse model." (PMID 30075819, 2018). "Tumor tissues derived from RIF1 knockdown H1299 cells exhibited decreased positivity for β-catenin and MYC compared with the control groups, indicating that RIF1 promoted Wnt/β-catenin signaling in the mouse model." (PMID 30237512, 2018). "There was also slower RIF-1 EGFP rechallenge growth but no rejection when RIF-1 EGFP tumours were surgically removed." (PMID 16421588, 2006). "The RIF-1 EGFP tumours disappeared completely by day 20 and did not return during the 40 days they were followed." (PMID 16421588, 2006). "The extracellular volume fraction measured by radiolabelling of RIF-1 tumours was 23 +/- 0.83% (mean +/- s.e.m. n = 9), not significantly different (P > 0.1) from that found by MRS (27 +/- 2.9%, n = 9, London, and 35 +/- 6.7, n = 14, Baltimore)." (PMID 9744499, 1998). "The baseline level of immunogenicity of the EGFP expressing tumours is confirmed by the data that a rechallenge of mice whose RIF-1 EGFP tumours had been surgically removed with the same RIF-1 EGFP cells led to a significantly reduced rate of tumour growth but no outright rejection." (PMID 16421588, 2006). "The increases in GRE image intensity of the MNU, H9618a and GH3 tumours during carbogen breathing are consistent with increases in tumour oxygenation and blood flow, whereas the responses of the RIF-1 and HT29 tumours may be the result of a transient steal effect followed by homeostatic correction." (PMID 9083335, 1997).